THADA (THADA armadillo repeat containing)
Description:
Together with methyltransferase FTSJ1, methylates the 2'-O-ribose of nucleotides at position 32 of the anticodon loop of substrate tRNAs.
Synonyms: GITA; KIAA1767; FLJ21877; ARMC13; Trm732
Tractability: PROTAC: ubiquitination databases record sites on it; its protein half-life has been measured.
Gene: Protein-coding gene on chromosome 2 (43,230,836 to 43,596,051, reverse strand). Ensembl gene ENSG00000115970.
Subcellular location (Human Protein Atlas): Cytosol
Pathways (Reactome):
Metabolism of RNA: tRNA modification in the nucleus and cytosol
Gene Ontology:
Molecular function: enzyme regulator activity; protein binding
Biological process: lipid homeostasis; negative regulation of endoplasmic reticulum calcium ion concentration; tRNA methylation; tRNA nucleoside ribose methylation; adaptive thermogenesis
Cellular component: cytoplasmic side of endoplasmic reticulum membrane
Genetic constraint (gnomAD): Loss-of-function variants: 187 observed, 179.18 expected, observed/expected ratio (o/e) 1.04, 90% interval 0.93 to 1.18. The synonymous counts are far from expectation, so gnomAD's model fits this gene poorly and the ratio says little. Missense variants: 2,696 observed, 2,145.5 expected, observed/expected ratio (o/e) 1.26, 90% interval 1.22 to 1.3. Synonymous variants: 928 observed, 779.58 expected, observed/expected ratio (o/e) 1.19, 90% interval 1.13 to 1.26.
Homologues: Orthologues: chimpanzee THADA (99% identical), macaque THADA (96% identical), dog THADA (83% identical), rabbit THADA (81% identical), guinea pig THADA (80% identical), rat Thada (79% identical), mouse Thada (78% identical), tropical clawed frog thada (53% identical), Drosophila melanogaster THADA (21% identical), Caenorhabditis elegans Y92H12A.5 (16% identical), zebrafish thada (6% identical).
Diseases named in the same sentence as THADA in open-access papers:
THADA is named in the same sentence as 43 diseases in open-access papers, as found by Europe PMC text mining. Sharing a sentence is not in itself a finding about the gene and the disease. The quoted sentences say what the papers report.
type 2 diabetes (23 papers, 2008 to 2025). "THADA has been identified as a type 2 diabetes-associated gene whose function is not fully understood." (PMID 36823211, 2023). "To date, the association of THADA rs7578597 T>C with diabetes type 2 risk has been assessed, but the results are inconsistent." (PMID 36672824, 2022). "The Thyroid Adenoma Associated (THADA) gene has been identified as one of the genes associated with the risk of developing type 2 diabetes." (PMID 36672824, 2022). "In a Mexican population, rs7578597 T>C and THADA were significantly associated with obesity, glycemic, and lipid phenotypes in patients with type 2 diabetes." (PMID 36672824, 2022). "The gene CG15618 has been identified as the Drosophila ortholog of THADA (Thyroid adenoma-associated protein homolog), the latter being identified as one of the top risk loci for type 2 diabetes in human genome-wide association studies." (PMID 33143302, 2020). "The thyroid adenoma-associated protein encoded by the THADA gene is expressed in many organs.One GWAS reported the association of THADA with type 2 diabetes particularlythrough a probability effect on pancreatic beta-cell function." (PMID 31902981, 2019). "examine the function of THADA, a positively selected gene in human evolution associated with type 2 diabetes, in Drosophila and show that THADA modulates, via calcium signaling, energy storage and thermogenesis balance." (PMID 28399403, 2017). "Previous studies have suggested that the THADA gene may be associated with an increased risk of developing type 2 diabetes." (PMID 36672824, 2022). "THADA was also identified as one of the top risk loci for type 2 diabetes by GWAS." (PMID 28399403, 2017). "GWAS identified THADA as one of the top risk loci for type 2 diabetes." (PMID 28399403, 2017). "Since THADA has been associated with type 2 diabetes, we asked whether THADA regulates organismal metabolism." (PMID 28399403, 2017). "The module related to type 2 diabetes contains three genes with significant P-values (THADA, PTPLA, HSD17B12) and three with P < .05." (PMID 37860106, 2023). "A recent analysis suggested that the same genetic variant alters risk of both type 1 and type 2 diabetes in five regions, near CENPW, CTRB1/BCAR1, GLIS3, BCL11A and THADA." (PMID 33830302, 2021). "Although THADA is known to play a role in cold adaptation, obesity, and type 2 diabetes, its role in thyroid function remains elusive." (PMID 32769997, 2020). "And meta-analysis on three Caucasian GWAS yielded six additional loci (JAZF1, TSPAN8-LGR5, THADA, ADAMTS9, NOTCH2-ADAM30 and CDC123-CAMK1D) associated with type 2 diabetes at genome-wide statistic significance." (PMID 19862325, 2009). "A very recently published study investigated associations of the type 2 diabetes risk alleles in JAZF1, CDC123/CAMK1D, TSPAN8/LGR5, THADA, ADAMTS9, and NOTCH2 with obesity, insulin sensitivity, and insulin secretion in 4516 Danes." (PMID 18714373, 2008). "The THADA gene is related to phenotypes such as platelet count and type 2 diabetes." (PMID 39457566, 2024). "Combined, these data suggest that the primary effect of altered THADA activity and calcium signaling is on lipid metabolism, and that a combination with high-fat feeding may be required to lead to type 2 diabetes over time." (PMID 28399403, 2017). "For instance, the role of MTNR1A and MTNR1B, THADA, CAPN10, and PPAR-γ2 in pathology of type 2 diabetes and obesity has been confirmed." (PMID 34949963, 2021). "Gene association studies have so far identified 16 candidate loci involved in PCOS, including genes involved in gonadotropin action (LHCGR and FSHR), metabolism and sexual development (ESR1), insulin signaling and type 2 diabetes (INSR, THADA, HMGA2) or cell proliferation (YAP1 and SUMO1P1)." (PMID 40551954, 2025).
type 2 diabetes (continued). "We did not replicate the finding that the chromosome regions near CENPW, GLIS3, BCL11A or THADA co-localised between type 1 and type 2 diabetes (H4PP CENPW=0.12, GLIS3=0.29, BCL11A=0.28, THADA not examined as no type 1 diabetes association existed in the region [FDR=0.07])." (PMID 33830302, 2021). "A 6-month training study in males with and without a family history of type 2 diabetes showed decreased DNA methylation of genes with known function in muscle and type 2 diabetes, including MEF2A, RUNX1, NDUFC2, and THADA, decreased after exercise." (PMID 35323665, 2022).
Obesity (14 papers, 2008 to 2024). Accumulation of substantial excess body fat. "We find that THADA mutation leads to obesity due to roles of THADA both in the fat body and in neurons." (PMID 28399403, 2017). "Loss of expression of AmyD (N = 2, Change in FC50 = 0.37 ± 0.02) and THADA (N = 2, Change in FC50 = 0.13 ± 0.18) both resulted in decreased FC50, which is associated with increased fat content and enhancement of the obesity phenotype." (PMID 39196987, 2024). "Our investigation revealed relationships between THADA and THADA-AS expression with diabetic and obesity-abdominal obesity phenotypes, as well as dynamic expression in adipogenesis." (PMID 37326626, 2023). "This mild, ubiquitous knockdown of SERCA completely reversed the obesity of THADA mutants, indicating that the obesity is indeed a result of improved ER calcium pumping in these animals." (PMID 28399403, 2017). "The combination of cold sensitivity and obesity in THADA mutant animals is interesting in terms of the evolutionary origins of the current obesity pandemic." (PMID 28399403, 2017). "This interaction between THADA and SERCA appears to be an important part of THADA function, since the obesity phenotype of THADA mutants can be rescued by mild SERCA knockdown." (PMID 28399403, 2017). "THADA thereby provides a genetic and molecular link between climate adaptation and obesity." (PMID 28399403, 2017). "Thus, THADA may play a UCP1-independent role in thermogenesis and cold adaptation and may thus influence ethnic variations in obesity susceptibility." (PMID 30723844, 2019). "Reducing SERCA activity in THADA mutant flies rescues their obesity, pinpointing SERCA as a key effector of THADA function." (PMID 28399403, 2017). "THADA mutant flies lacking in SERCA activity were cold sensitive and prone to obesity." (PMID 30723844, 2019).
Thyroid adenoma (14 papers, 2008 to 2025). The presence of a adenoma of the thyroid gland. "The gene of Thyroid adenoma associated (THADA) was identified as a target gene affected by chromosome 2p21 translocations in thyroid adenomas, and encodes the hypothetical 1954 amino acids (220 kDa)." (PMID 38561668, 2024). "Thyroid adenoma-associated gene (THADA) was highly expressed in GC tissues from chemotherapy-sensitive patients and was an independent prognostic factor in GC patients receiving postoperative 5-FU adjuvant chemotherapy." (PMID 38234670, 2024). "Three kinds of cardiac glycosides (ouabain, oleandrin, and digoxin) inhibited the cancer cell proliferation and decreased the expression level of thyroid adenoma-associated protein (THADA)." (PMID 38561668, 2024). "At the gene level, two genome-wide significant genes [MACF1 and THADA (thyroid adenoma associated)] were associated with migraine and T2D." (PMID 35627115, 2022). "An intronic variant (rs10186921) in the thyroid adenoma-associated gene THADA was identified to be associated with TSH." (PMID 32769997, 2020). "Thyroid adenoma associated (THADA) has been identified as the target gene affected by chromosome 2p21 translocations in thyroid adenomas, but the role of THADA in the thyroid is still elusive." (PMID 22050638, 2011). "THADA (thyroid adenoma associated) was identified as the affected gene within this breakpoint region." (PMID 18522714, 2008). "Interestingly, up to five gene fusions are involved in THADA armadillo repeat containing (THADA), which stands for thyroid adenoma-associated gene." (PMID 38779099, 2024). "THADA (thyroid adenoma associated), was initially identified in thyroid adenomas." (PMID 32425888, 2020). "In total, 12 of the 65 reported T2D GWAS loci are significantly differentially methylated (FDR 25%), and these include well-documented T2D loci such as those near IGF2BP2 (Insulin-like growth factor 2 mRNA-binding protein 2) and THADA (thyroid adenoma-associated gene)." (PMID 25502755, 2014). "The target gene has been identified and referred to as thyroid adenoma associated (THADA)." (PMID 22050638, 2011). "Recently, a gene named THADA (thyroid adenoma associated) [GenBank: NM_022065] which is directly affected by this cytogenetic rearrangement, could be identified within the 2p21 breakpoint region." (PMID 18522714, 2008). "In order to elucidate if the THADA gene is also a target of chromosomal rearrangements in thyroid adenomas of the dog we have physically mapped the canine THADA gene to canine chromosome 10." (PMID 18522714, 2008). "The proposed candidate gene for rs7590268 is THADA (Thyroid adenoma associated), although it has no known function in craniofacial development." (PMID 30405682, 2018). "Another gene with CR-APA, THADA, has been hypothesized to contribute to the tumorigenesis of thyroid adenomas in its truncated form." (PMID 24782827, 2014). "In order to elucidate whether canine THADA could be a candidate gene for a possible malignant transformation of canine thyroid adenomas further cytogenetic studies of the tumours could be of significant value." (PMID 18522714, 2008). "We analysed whether the THADA gene locus is a hotspot of canine chromosomal rearrangements in canine neoplastic lesions of the thyroid and in addition might play a role as a candidate gene for a possible malignant transformation of canine thyroid adenomas." (PMID 18522714, 2008). "Although the available cytogenetic data of canine thyroid adenomas are still insufficient the chromosomal region to which the canine THADA has been mapped seems to be no hotspot of chromosomal aberrations seen in canine thyroid adenomas." (PMID 18522714, 2008).
polycystic ovary syndrome (7 papers, 2013 to 2025). A disorder that manifests as multiple cysts on the ovaries. "Genome-wide association studies (GWAS) have identified THADA as one of the susceptibility genes for polycystic ovary syndrome (PCOS)." (PMID 35480478, 2022). "A recent genome-wide association study (GWAS) of polycystic ovary syndrome (PCOS) in European cohorts has identified six susceptibility loci mapping to 11q22.1 (YAP1), 2p21 (THADA), 11p14.1 (FSHB), 2q34 (ERBB4), 12q21.2 (KRR1), and 5q31.1 (RAD50)." (PMID 28195137, 2017).
diabetes (6 papers, 2011 to 2023). "The data presented here indicate that THADA regulates lipid metabolism and feeding, suggesting that the association between THADA and diabetes may be causal in nature." (PMID 28399403, 2017). "Here the authors report that THADA deficiency protects mice from hyperglycemia and glucose intolerance by promoting insulin secretion and inhibiting β-cell apoptosis, suggesting THADA could be explored as a potential therapeutic target for diabetes." (PMID 36823211, 2023). "Its expression level in islet was indistinguishable between 4-week-old prediabetic db/db mice and wild-type littermate controls, but gradually increased when the db/db mice progressed into T2DM at 8 and 16 weeks, indicating THADA is activated during diabetes progression." (PMID 36823211, 2023). "Further indication for a correlation between THADA and T2D was presented in several other publications, one reported an altered expression of THADA in pancreatic islets, using data from the Diabetes Genome Anatomy Project (DGAP) database." (PMID 22050638, 2011).
thyroid cancer (6 papers, 2011 to 2025). "In thyroid cancer, the fusion of THADA gene with LOC389473 gene leads to abnormal IGF2BPs expression, activating the IGF1R signaling pathway, and promoting the proliferation and invasion of cancer cells." (PMID 40088376, 2025).
Insulin resistance (5 papers, 2017 to 2023). Increased resistance towards insulin, that is, diminished effectiveness of insulin in reducing blood glucose levels. "Studies have suggested an effect of the THADA gene on insulin secretion and insulin resistance, as well as an effect on body mass index." (PMID 36672824, 2022). "PCOS susceptibility variants in THADA and INSR are associated with metabolic syndrome and variants in TOX3 and DENND1A are associated with insulin resistance." (PMID 32425888, 2020). "Taken together, the data point to a relationship between the THADA locus in PCOS and the independent causal association with insulin resistance and metabolism." (PMID 28068351, 2017). "This genotype-phenotype study provides clues that THADA, INSR, TOX3, and DENND1A play important role in the etiology of PCOS, possibly through insulin resistance and metabolic disorder related pathways." (PMID 32425888, 2020).
adenoma (4 papers, 2019 to 2024). A neoplasm arising from the epithelium. "We discuss the THADA gene (also called thyroid adenoma-associated protein) separately, located on the short arm 2p21 of chromosome 2, first discovered in thyroid tumors." (PMID 34795691, 2021). "In this study, we identified a significant single nucleotide polymorphism (SNP) (Chr27:13604716) located within the exon region of the Thyroid Adenoma Associated gene (THADA) on Chr27, which showed a significant association with the semi-submerged length trait in geese." (PMID 39736931, 2024). "THADA, (thyroid adenoma-associated protein) (lead SNP: rs7590268) a protein coding gene, is the known target of 2p21 chromosomal aberrations in benign thyroid adenomas and the encoded protein is possibly involved in the death receptor pathway as well as apoptosis." (PMID 36672757, 2022).
migraine (4 papers, 2022 to 2023). "Additionally, among the overlapping genes between migraine and headache with glycemic traits, five genes have previously been associated with migraine (THADA, EHMT2, AMBRA1, and SMG6) and headache (ATG13); now, these genes are also implicated in glycemic traits." (PMID 36808568, 2023). "Furthermore, five of the 30 genome-wide significant genes overlapping migraine and more than one glycemic trait were the nearest genes to a lead migraine SNP (THADA, EHMT2, AMBRA1, and SMG6) and headache SNP (ATG13)." (PMID 36808568, 2023). "ITPK1, THADA, and ZNF652 have also been reported to be GWS in the recent TSH GWAS implying that these genes are important in headache, migraine, and thyroid traits physiology." (PMID 36672757, 2022). "Interestingly, some of these loci mapped to genes including ITPK1, ZNF462, RPL30P1, ANKDD1B, THADA, ZNF652, and C20orf203 that have been reported as genome-wide significant in the most recent migraine GWAS." (PMID 36672757, 2022).
thyroid tumor (4 papers, 2011 to 2023). A benign or malignant neoplasm affecting the thyroid gland. "These mutations are RET/PTC and THADA/IGF2BP3 translocations, which have been hypothesized as oncogenic events in thyroid neoplasms." (PMID 37444504, 2023). "Furthermore, in thyroid tumors THADA mRNA expression was found to be inversely correlated with HMGA2 mRNA." (PMID 22050638, 2011). "This study investigated the impact of two gene fusions, RET/PTC and THADA/IGF2BP3, that have been described as oncogenic events in thyroid neoplasms." (PMID 37444504, 2023).
hyperandrogenism (3 papers, 2019 to 2024). Excessive secretion of androgens from the adrenal glands or gonads. "In genotype-phenotype correlational analysis, the THADA gene contributed to hyperandrogenism in PCOS." (PMID 35480478, 2022). "Subsequent genotype–phenotype correlational analysis found that the THADA gene contributes to hyperandrogenism in PCOS with Han Chinese ancestry." (PMID 31623391, 2019). "THADA was shown to have metabolic contributions to the pathophysiology of PCOS, such as disorders of glucose metabolism, hyperandrogenism, and dyslipidemia, which could also contribute to hypertensive disorders of pregnancy." (PMID 39006363, 2024).
Hyperglycemia (2 papers, 2023 to 2025). An increased concentration of glucose in the blood. "Importantly, THADA deficiency protects mice from high-fat high-sucrose diet- and streptozotocin-induced hyperglycemia by restoring insulin secretion and preserving β-cell mass." (PMID 36823211, 2023). "Recalling our finding that loss of THADA led to improved glucose homeostasis in mice, we hypothesized that THADA deficiency might protect mice from diet-induced hyperglycemia." (PMID 36823211, 2023). "THADA knock-out in mice enhances β-cell function and reduces β-cell apoptosis, protecting against high-fat high-sucrose and streptozotocin-induced hyperglycemia." (PMID 40422193, 2025). "By exploiting a high-content screen targeting THADA’s function in reducing [Ca2+]i, we further identified a natural compound, alnustone, capable of improving β-cell function and alleviating hyperglycemia in DIO mice." (PMID 36823211, 2023). "Moreover, treatment with alnustone inhibits THADA’s function, resulting in ameliorated hyperglycemia in obese mice." (PMID 36823211, 2023). "Importantly, treatment with alnustone, an inhibitor of THADA protein’s function, ameliorates hyperglycemia in obese mice, suggesting that THADA protein could be a potential target for developing T2DM therapies." (PMID 40422193, 2025).
type 1 diabetes (2 papers, 2021 to 2022). "We did not replicate the findings that the associations near BCL11A, CENPW and THADA co-localise between the two diseases, despite overlapping samples and similar numbers of cases and controls in the type 1 diabetes GWAS." (PMID 33830302, 2021).
colon cancer (1 paper, 2024). "Additionally, a study identified that THADA is a key regulator in maintaining PD-L1 expression in colon cancer, with THADA expression in colon cancer tissues exhibiting a positive correlation with PD-L1 expression." (PMID 38234670, 2024).